CD4 (CD4 molecule)
Diseases named in the same sentence as CD4 in open-access papers (continued):
Sharing a sentence is not in itself a finding about the gene and the disease.
tumor (continued). "Moreover, the T cell infiltrations of CD3+, CD4+, and CD8+ T cells, as well as their anti‐tumor capacity, were amplified via immune‐suppression microenvironment reversion through high‐effective collagen, PD‐L1, and TGF‐β co‐inhibition by IR‐LND@Lip in vivo." (PMID 38704675, 2024). "We found that infiltration of CD4+ T cells, as well as Foxp3+CD4+ T cells in tumour tissue, gradually increased from no to high PD-L1 IC; this increase was primarily driven by the high PD-L1 expression group." (PMID 38541208, 2024). "A substantial proportion of CD4+ T cells from central (median 34%) and peripheral (median 27%) tissues were single positive (SP) for CD39, and this population was significantly lower in non-tumor tissues (median 11%)." (PMID 38335302, 2024). "Since probiotics have demonstrated their ability to modulate human immune defenses against pathogens and tumor cells and are essential for overall immune system responses, the increased numbers of CD3 + T cells, CD8 + T cells, and CD4 + T cells in the A-CCRT-P group underscore their importance." (PMID 39030525, 2024). "Conversely, CD8 T cells primed in the absence of CD4 help are functionally impaired, abrogating tumor control." (PMID 38903502, 2024). "Furthermore, BTLA + CD4 + T-cells produced less IL-2 compared to those from healthy mice, while BTLA + CD8 + T-cells in tumor- bearing mice had impaired IL-2 and TNF production." (PMID 38233898, 2024). "For cell viability, 75% of HVEM+ K562 tumor cells remained alive after co-culturing with CFSE CD4+ T cells as a result of not treating them with an HVEM blocker." (PMID 38785930, 2024). "Additionally, we investigated the correlation between the expression of these different factors (lymphocytes, CD3+ T, CD4+ T, CD8+ T, and CD19+ B) and tumor indicators CA724, CA199, and CEA." (PMID 38259671, 2024). "In the mouse H22 tumor model, the expression levels of CD4 and CD8 were higher in both groups B and C than in group A (P < 0.05), while in group D, the expression levels of CD4 and CD8 were significantly higher than in groups A and C (P < 0.05)." (PMID 38532022, 2024). "Another investigation found no substantial variance in the distribution of CD4+ T cells surrounding and within the tumor." (PMID 39845973, 2024). "To further explore whether T lymphocytes mediate the anti‐tumor effect of LSS, we continued to examine the changes of tumor T lymphocytes, including CD8+ and CD4+ T lymphocytes, by flow cytometry." (PMID 38606362, 2024). "IHC experiments showed that MC38-sh-circNCOA3-derived tumors presented a high amount of CD8+, but not CD4+, tumor-infiltrating lymphocytes (TILs) and reduced infiltration of myeloid-derived suppressor cells (MDSCs)." (PMID 38510750, 2024). "This array of proteins contains epitopes for CD4+ and CD8+ T cells, facilitating MHC classes I and II presentation, and promoting a broad anti-tumour immune response that may reduce chances of tumour escape and development of resistance." (PMID 38223410, 2024). "In contrast, TA-specific interleukin (IL)-4-producing CD4+ T helper (Th2) cells evolved as a negative prognostic marker within the tumor microenvironment (TME) as they promote tumor growth by enhancing angiogenesis and inhibiting cell-mediated immunity 24-26." (PMID 39239511, 2024). "Therefore, the presence of macrophages, CD4+ T cells, and CD8+ T cells in spleen and tumor tissues was analyzed using flow cytometry." (PMID 38891683, 2024). "LAG-3 and PD-1 have been detected to be co-expressed on CD4+ and CD8+ TILs in preclinical mouse tumor models, suggesting that their co-blockade of the LAG-3 and PD-1 signaling pathways can enhance the proliferation of tumor-specific CD8+ T cells and cytokine release." (PMID 38627681, 2024). "CD4+ T cells can recognize tumor cells and interact with CD8+ T cells to suppress tumor growth." (PMID 38560565, 2024).
tumor (continued). "The results showed that HVEM+ K562 tumor cells expanded normally when they were cultured alone or co-cultured with CFSE CD4+ T cells without HVEM blocker treatment of the tumor cells." (PMID 38785930, 2024). "Meanwhile, it was found that Epi0 may chemotaxis CD4+ Tn into the TME via CXCL14-CXCR4, which subsequently differentiated into Tfh and Th17, inducing the formation of a tumor inhibitory immune microenvironment." (PMID 39093451, 2024). "CD4+ Th1-polarized effector memory cells expressing CXCR3 and CCR5, the receptors for CXCL9/10/11 and CCL5, respectively, are another significant component of tumor-infiltrating lymphocytes (TILs)." (PMID 39114657, 2024). "In addition, we also found that CD4+ and CD8+ T cells secreted PD-1, granzyme B, CD107a and TNF-α levels in tumor tissues of KC;Ubr7–/– mice were significantly reduced." (PMID 39424627, 2024). "Even though this could not be confirmed in this case, the MHC-II-positive tumors displayed a significant CD4+ T lymphocyte infiltration, suggesting the involvement of an MHC-II-restricted CD4+ TH cell activation against tumor antigens." (PMID 39035008, 2024). "Moreover, FL cells are involved in the recruitment of CD4+ T regulatory cells (TREG), in charge of inhibiting anti-tumor immune responses, hampering CD8+ granzyme B and perforin release." (PMID 38697976, 2024). "Moreover, flow cytometry analysis of T cells in tumor tissues treated with PAC-SABIs demonstrated a significant increase in the percentage of tumor-infiltrating CD8+ and CD4+ T cells." (PMID 38971872, 2024). "Positive correlations were found between the expression of 5-LOX in tumour cells with TG2 (r = 0.34, p = 0.010), CD3 (r = 0.32, p = 0.013), CD4 (r = 0.47, p < 0.001), and CD8 (r = 0.27, p = 0.039), respectively, whereas 5-LOX in tumour cells negatively correlated to GzmB (r = -0.35, p = 0.006)." (PMID 38816839, 2024). "After tumor resection (T1), a recovery in the absolute counts of CD4+ Treg cells from CCA and HCC patients is observed, suggesting that, after tumor removal, the active migration of Treg cells to the liver ceases, and the Treg cell population in the peripheral blood is replenished." (PMID 39408071, 2024). "Tumor-specific sympathetic denervation in a mouse xenograft model and in a rat model with chemically induced tumors showed a marked decrease in the PD-1 and PD-L1 expressions on CD8+ and CD4+ T lymphocytes." (PMID 38334648, 2024). "In addition, the IAP inhibitor M1 enhances the response of CD4+ CD8+ T cells, and other anti-tumor effector cells and the combination with B16 vaccines (GVAX) improves the efficacy of tumor vaccines." (PMID 39253578, 2024). "Acetylcholine (Ach) is produced by enteric neurons and intestinal nonneuronal cells, such as CD8 + cells, CD4 + cells, NK cells, epithelial cells, and tumor colon cells." (PMID 38867310, 2024). "In contrast, for their helper function, CD4+ cells do not necessarily need to be in contact with the tumor cells but they need to be in the proximity of cancer cells." (PMID 38054651, 2024). "Additionally, M1 macrophages stimulate T cells, improve the expression of CD4 and CD8, induce immune responses against tumor cells, and inhibit tumor formation." (PMID 39309874, 2024). "Activated CD4 T cells provide not only CD40L, but also IFN-I, which act nonredundantly to cross-prime cDC1s against tumor cell-associated antigens." (PMID 39050844, 2024). "GSDME expression was significantly and negatively correlated with the tumor purity of LIHC (p < 0.05), while it was significantly and positively correlated with the degree of infiltration of B cells, CD8+ T cells, CD4+ T cells, macrophages, neutrophils and dendritic cells." (PMID 38434972, 2024).
tumor (continued). "Because TILs were associated with response to atezolizumab plus carboplatin, we developed multiplex-immunofluorescence assays to evaluate tumor-specific (pan-CK), PD-L1, and MHC-I expression, as well as effector (CD8) and helper (CD4) T-cell subsets (eFigure 9A-9D in Supplement 2)." (PMID 38095878, 2024). "This negative correlation between the expression level of MAGEA3 and central CD4 + T cells, CD8 + T cells and Th17 cells using TISIDB database.These results indicated that MAGEA3 might have an important effect on tumor immune infiltration in LUAD." (PMID 38555374, 2024). "Our data suggest that therapies aimed at generating CD4+ dependent anti-tumour T cell responses should not target B cells alone." (PMID 38125720, 2024). "Interestingly, immune cells percentage in single treatment of anti-CD4 antibody group dropped to anti-CD4 and anti-CD8 group, indicating that CD4+T cells induced tumor inflammation." (PMID 38956432, 2024). "Moreover, CD4+CD57+ T cells were higher within the CVH and ARLD groups compared to peri-tumor tissues." (PMID 39944754, 2024). "This is a clear contrast to CD8+ T cells of these mice described earlier, whereas IFN-γ levels in the supernatants of the immunized CD4+ T cells cultured with MC38 cells were greater than those detected in their cultures without the tumor cells (p < 0.0001)." (PMID 38247803, 2024). "A previous study reported a non-inflamed tumor microenvironment (TME) with high CD4+ Treg cell infiltration in pre-treated EGFR-mutant NSCLC." (PMID 38897205, 2024). "Increased levels of CD4+ and CD8+ T cells, NK, NKT, and B cells were seen in the tumor." (PMID 38803496, 2024). "The remaining subjects in the immune-reconstituted vehicle control group were caspase negative, as tumor cells were not present, although an increase in CD-3, CD-4, and CD-68 staining was observed in the tumor transplant area." (PMID 39200298, 2024). "Flow cytometry was utilized to assess the levels of CD4, CD8, and CD161 in tumor samples." (PMID 39580409, 2024). "Furthermore, examination of tumor‐draining lymph nodes showed an increase in CD8+ T cells in the PS‐treated group, with more CD4+ T cells expressing TNFα." (PMID 38900071, 2024). "All cases showed tumor CD30 expression, whereas CD4 and CD8 expressions were inconsistent." (PMID 38780761, 2024). "The identification of HLA-II neoantigens enables HLA-II neoantigen vaccination and may benefit patients, as CD4+ T cells reactive to the HLA-II neoantigen (KVY15) identified by NESSIE produced IFN-γ and TNFα, suggesting their role in preventing tumor growth." (PMID 39292790, 2024). "Furthermore, our study indicated positive correlations between ARL-6 expression levels and the activities of tumor-infiltrating immune cells such as B cells, myeloid dendritic cells, macrophages, neutrophils, CD8+T cells, and CD4+T cells." (PMID 38169538, 2024). "The purpose of this study was to investigate the effects of T. gondii excretory‐secretory antigens (ESA) on CD4 + CD25+ Foxp3+ Treg cells in mice with LLC and to determine whether T. gondii ESA inhibits tumor growth." (PMID 38109851, 2024). "Regulatory T cells can thereby prevent the anti-tumor immune response by inhibiting the function of both tumor-specific effector cells (natural killer cells and NK T cells) and tumor-unspecific effector cells (CD8+ cytotoxic T lymphocytes and CD4+ T helper cells)." (PMID 38314272, 2024). "These processes suppress anti-tumor CD8+ and CD4+ T cells by inhibiting the TCR." (PMID 39609700, 2024). "Within the CD4+ T cell compartment, there were more T effector/memory (TEM; CD44+, CD62L-) and less T regulatory (Treg; FoxP3+) cells in CR705Parp7KO compared with CR705Cas9 tumours." (PMID 39867896, 2024). "Moreover, the cytotoxic T-lymphocyte anti-tumor immune effects were verified by the elevated expression of CD3+, CD3+CD4+, and CD3+CD8+ T lymphocytes." (PMID 38791452, 2024).
tumor (continued). "Recent studies also report that CCR7+ DCs may engage other immune cells in tumours, including CXCL13+ CD4+ T cells, regulatory T cells and NK cells, and may reside in TLS12,15." (PMID 38267413, 2024). "Additionally, HPV+ tumor cells expressing high MHC-II and CXCL13+CD4+ T cell prevalence are indicative of favorable overall survival rates in OPSCC patients." (PMID 39105803, 2024). "Furthermore, it was found that in Nets isolated from colorectal cancer patients with liver metastases, NETosis can induce CD4 and CD8 T‐cell exhaustion in the tumour microenvironment." (PMID 38652105, 2024). "On the other hand, compared with no-tumor control mice, presence of tumor led to increased CD4/CD8 ratio, suggestive of a more specific tumor-induced depletion of CD8T cells." (PMID 38351079, 2024). "Encouraged by the increased CD4+ and CD8+ T cell infiltration and up‐regulated expression levels of inflammatory factors in lung metastatic tumor nodules as shown by sectioning results, we investigated the anti‐tumor immune responses induced by ELeOVt." (PMID 37997186, 2024). "Tumor infiltrating CD45+immune cells was decreased after CD4+T cells depletion but not after CD8+T cells depletion." (PMID 38956432, 2024). "T cells are principal members of the adaptive immune system, and conventional T cells found in the TME consist of NK T cells, CD8+, and CD4+ T cells; CD8+ T (cytotoxic T lymphocytes) cells are the main tumor-infiltrating lymphocytes that operate anti-tumor activities." (PMID 39519285, 2024). "Tumor-infiltrating CD4 and CD8 T cells were indistinguishable in the overall gene expression profile, but T cells at the target lesion differed from those at the non-target lesion." (PMID 39534532, 2024). "To investigate whether IFNβ produced by CD4+ T cells plays a role in the cDC1-mediated CTL response in humans, we employed our in vitro tumor antigen-specific CTL priming platform." (PMID 38383773, 2024). "Following activation by myeloid cells in tumour‐draining lymph nodes (dLNs), CD4+ and CD8+ T cells differentiate into various tumour‐infiltrating lymphocytes (TILs), encompassing T helper (Th1/Th2/Th17) cells, Tregs and Tfh cells (CD4+ CXCR5+ PD‐1high), among others." (PMID 38451000, 2024). "Neoantigen expression is required to generate anti-tumour CD8 and CD4 T cell responses." (PMID 39025846, 2024). "Although further investigation is still needed, we found that depletion of CD8+ T cells, but not CD4+ T cells, significantly abrogated anti-tumor activity using an updated version of mHTV-02 (data not shown)." (PMID 38514186, 2024). "On the contrary, it is neither correlated with the density of CD8 T cells in the tumour nest nor the CD4 T cells in the tumour stroma or nest." (PMID 39061159, 2024). "Although we did not observe a significant change in the tumor infiltration of CD4+ T cells, it is worth noting that CEP55 KO-derived tumors showed a significantly elevated CD8+ T cell infiltration." (PMID 38250876, 2024). "Additionally, tumours treated with triple combination for 2 weeks were characterised by an elevated infiltration of CD8+ and CD4+ T cells." (PMID 39322643, 2024). "Radiotherapy enhances the host immune system’s ability to recognize and eliminate tumor cells by upregulating MHC class I molecule expression on tumor cell surfaces, increasing CD8+ and CD4+ T lymphocyte infiltration, and improving tumor cell antigen recognition." (PMID 39839672, 2024). "In addition, we analyzed the TCR repertoire of CD4 + T cells and CD8 + T cells isolated from tumor tissues." (PMID 38280010, 2024). "Genetic knockout or blockage of the CGRP-RAMP1 pathway significantly inhibits tumor growth, and there is a notable increase in the infiltration of CD4+, CD8+, and NK1.1+ lymphocytes in the tumor tissue, enhancing the effectiveness of immune checkpoint inhibitors." (PMID 38567163, 2024).
tumor (continued). "The increase in CD4 + and CD8 + T cells following treatment suggests that CRT may foster anti-tumor immunity by recruiting these T cell subtypes into tumor tissues, potentially leading to improved patient prognoses." (PMID 38926205, 2024). "Building upon a recent study that unveiled the pivotal role of CD36 in regulating ferroptosis among tumor-infiltrating CD8+ T cells, the present study further identified the critical function of CD36 in mediating ferroptosis in CD4+ T cells, specifically within the context of ATAAD." (PMID 39266539, 2024). "Moreover, the authors showed some differential effects depending on the location of the tumor, and the relative contribution of CD4 and CD8 T cells to tumor rejection in depletion experiments." (PMID 39125578, 2024). "The analysis of distant and directly treated tumors revealed a significant increase in activated CD4+ and CD8+ T cells and tumor-specific CD8+ T cells upon intratumoral VSV-NDV treatment, demonstrating the transition from a “cold” to a “hot” tumor microenvironment." (PMID 39410025, 2024). "Furthermore, data analysis in the TIMER database revealed that the downregulation of KLRB1 expression was significantly positively correlated with tumor purity, and the levels of B cells, CD8+ T cells, CD4+ T cells, macrophages, neutrophils, and DC." (PMID 38782996, 2024). "This in turn increases CD4 + and cytotoxic CD8 + T cell infiltration of the tumor." (PMID 38561369, 2024). "Therefore, the proportion of immune cells including CD4+, CD8+ T cells, and NK cells, the major IFNγ producers, were analyzed in the B16F10 tumor model at the early stage (1, 3, 5, 7d) post ablation." (PMID 38827732, 2024). "Evaluating PD-L1 expression and TILs in the TME, significant correlation between PD-L1 IC and CPS, but not TPS and the number of tumour-infiltrating CD4+ T cells, Foxp3+CD4+ T cells, and CD8+ T cells were detected." (PMID 38541208, 2024). "However, tumor-bearing WT mice and CD11c:DTA mice showed comparable accumulations of CD4+Foxp3+ Treg cells and CD4+Foxp3+RORγt+ Treg cells in tumor tissues." (PMID 39206204, 2024). "Immunohistochemistry was employed to detect CD4+ and CD8+ T cells in tumor tissues." (PMID 39458338, 2024). "We know roughly from previous research that PD-1 is expressed on the surface of various immune cells, including activated CD4+ T cells, CD8+ T cells, B cells, natural killer T cells, monocytes, and dendritic cells DCs) while PD-L1 and PD-L2 are mainly expressed in tumor cells." (PMID 39120585, 2024). "A vital subgroup of CD4 T-cells known as regulatory T-cells (Tregs) are typified by the CD4 + CD25 + Forkhead box P3+ (FoxP3+) phenotype and are capable of modulating peripheral tolerance as well as responses to foreign and tumor antigens." (PMID 38672732, 2024). "There was a trend for psyllium plus inulin-treated mice having higher levels of systemic helper T and cytotoxic T cells compared to psyllium plus RS-treated (p = 0.0882 for CD4+ T cells and p = 0.1085 for CD8+ T cells), consistent with the local tumour immune analysis." (PMID 38745230, 2024). "This is noteworthy because CD4+ T cells possess inherent cytotoxicity, allowing them to directly target tumor cells even without assistance from CD8+ T cells." (PMID 38791916, 2024). "Interestingly, for CD4 and CD8α the average intensity/cell is consistently lower in 4T1 and B16F10 tumor models relative to the CT26 tumor model." (PMID 38605049, 2024). "This process enhances the activation of effector CD4+ and CD8+ T cells in both the TDLNs and the tumour, as well as increases leukocyte infiltration and the proportion of IFN-γ and Granzyme B-producing CD8+ T cells in the tumour." (PMID 39337605, 2024). "Using flow cytometry–based immunoprofiling, we examined changes in viable T lymphocytes (CD3+), helper T cells (CD3+/CD4+), and cytotoxic T cells (CD3+/CD8+) in the baseline PBMCs versus in the immune cells isolated from the cocultures (tumor-stimulated immune cells, “ts-immune”)." (PMID 39475596, 2024).